JAK2 (Janus kinase 2)
Diseases named in the same sentence as JAK2 in open-access papers (continued):
Sharing a sentence is not in itself a finding about the gene and the disease.
myeloproliferative neoplasm (continued). "Systemic risk factors include inherited thrombophilias such as factor V Leiden, prothrombin 20210A, protein C/S deficiency, antithrombin III deficiency, antiphospholipid syndrome, and JAK2-mutated myeloproliferative disorders." (PMID 40821172, 2025). "The development of targeted therapies was strongly supported by two key findings: gene knock-out studies and the clinical discovery of activating JAK mutant forms (e.g., the JAK2 V617F mutation in myeloproliferative disorders)." (PMID 41226376, 2025). "Myeloproliferative neoplasms (MPNs) encompass a diverse group of hematologic disorders driven by mutations in JAK2, CALR, or MPL." (PMID 38308077, 2024). "The JAK2 V617F somatic mutation is a hallmark of myeloproliferative neoplasms (MPN) and is present in some patients with splanchnic venous thrombosis (SVT)." (PMID 40777960, 2024). "As an example, the rs12343867 T > C SNP in intron 14 of Janus‐activated kinase 2 (JAK2) is associated with myeloproliferative neoplasms, functioning as a transcriptional repressor." (PMID 38520217, 2024). "The JAK2 p.V617F mutation is frequently detected in myeloproliferative neoplasms and has been associated with various complications." (PMID 38590525, 2024). "In particular, the JAK2 V617F somatic variant is frequently identified as a driver in adult-onset myeloproliferative neoplasms and is increasingly being associated with cardiovascular complications, including thoracic aortic aneurysms." (PMID 39062663, 2024). "Primary myelofibrosis (PMF) is an uncommon chronic myeloproliferative disorder that is commonly associated with Janus kinase 2 (JAK-2), calreticulin (CALR), or thrombopoietin receptor (MPL) mutations." (PMID 39759619, 2024). "Primary myelofibrosis (PMF) is a rare chronic myeloproliferative disorder that is commonly associated with Janus kinase 2 (JAK-2), calreticulin (CALR), or thrombopoietin receptor (MPL) mutations." (PMID 39759619, 2024). "Primary myelofibrosis (PMF) is a type of myeloproliferative neoplasm characterized by the clonal proliferation of stem cells, often accompanied by mutations in Janus kinase 2 (JAK2), calreticulin (CALR), or myeloproliferative leukemia (MPL) genes." (PMID 38983933, 2024). "Unfortunately, the patient was not eligible for ASCT because of severe bortezomib‐ and thalidomide‐induced neuropathy and JAK2‐mutated myeloproliferative neoplasm with marked splenomegaly." (PMID 39544101, 2024). "The JAK2 V617F somatic variant is a well-known driver of myeloproliferative neoplasms (MPN) associated with an increased risk for athero-thrombotic cardiovascular disease." (PMID 39062663, 2024). "JAK2-V617F mutation is frequently reported in myeloproliferative neoplasms (MPNs) such as polycythemia vera, essential thrombocythemia, and primary myelofibrosis." (PMID 39091915, 2024). "This study evaluated the association between the 46/1 haplotype and JAK2 V617F in patients with myeloproliferative neoplasms in a population from the Brazilian Amazon." (PMID 38654055, 2024). "JAK2 V617F (JAK2) mutation is associated with clonal hemopoiesis in myeloproliferative neoplasms as well as with faster progression of cardiovascular diseases." (PMID 39361963, 2024). "He did not receive autologous stem cell transplantation because of several comorbidities, such as severe drug‐induced neuropathy and JAK2‐mutated myeloproliferative neoplasm with marked splenomegaly." (PMID 39544101, 2024). "It has been described in mice models that myeloproliferative neoplasm (MPN) with JAK2‐V617F mutation has an increased expression of programmed death‐ligand 1 (PD‐L1) in megakaryocytes leading to cancer immune evasion by inhibiting the T‐lymphocytes." (PMID 39233645, 2024). "This case highlights the rare occurrence of portal vein thrombosis in a young patient with an underlying JAK2-positive myeloproliferative neoplasm." (PMID 39877786, 2024).
myeloproliferative neoplasm (continued). "Polycythemia vera (PV) is a myeloproliferative disease characterized by significantly higher hemoglobin levels and positivity for JAK2 mutation." (PMID 39188323, 2024). "Her BM biopsy result and JAK-2 mutation positivity confirmed the diagnosis of a myeloproliferative disorder, most likely PV." (PMID 39421127, 2024). "A meta-analysis has revealed that the prevalence of myeloproliferative disorder and Janus kinase 2 (JAK2) mutations in patients with PVT was 31.5% and 27.7%, respectively." (PMID 39114226, 2024). "Subsequently, a BM biopsy showed myeloproliferative neoplasm with features of PV, which were confirmed later by a positive test for JAK-2 mutation." (PMID 39421127, 2024). "The aetiology of BCS was identified in 63% of the cases, and myeloproliferative disorders defined by positive JAK2 mutation were the most common identifiable cause." (PMID 39407918, 2024). "Polycythemia vera (PV) is a myeloproliferative disorder characterized by significantly increased hemoglobin levels and JAK2 gene mutation." (PMID 39188323, 2024). "Specifically, JAK2 is involved in cytokine receptor signal transduction and is associated with several pathologies, such as myeloproliferative disorders." (PMID 39598448, 2024). "Polycythemia vera (PV) is a burdensome, chronic myeloproliferative neoplasm characterized by activating mutations in Janus kinase 2, erythrocytosis, and bone marrow hypercellularity." (PMID 36944847, 2023). "A V617F mutation in the JAK2 gene mutation is found in most patients with myeloproliferative neoplasms (MPNs)." (PMID 36959802, 2023). "The rs12343867 T>C SNP in intron 14 of Janus‐activated kinase 2 (JAK2) is associated with myeloproliferative neoplasms by acting as a transcriptional repressor." (PMID 37533175, 2023). "Myelofibrosis (MF) is a BCR::ABL1-negative chronic myeloproliferative neoplasm characterized by the presence of “driver” mutations in JAK2, CALR, and MPL genes." (PMID 37297002, 2023). "The Janus kinase 2 (JAK2)-driven myeloproliferative neoplasms (MPNs) are chronic malignancies associated with high-risk complications and suboptimal responses to JAK inhibitors such as ruxolitinib." (PMID 37423955, 2023). "The BRAFV600E-mutated patients also had myeloproliferative neoplasm (three chronic myelomonocytic leukemia and one JAK2-mutated essential thrombocythemia) compared to the BRAF wild-type group (36% vs. 0%; p = 0.046)." (PMID 37809108, 2023). "The molecular pathogenesis of BCR::ABL-negative myeloproliferative neoplasms was unascertained until 2005, when the presence of an activating point mutation in the JAK2 gene was first described." (PMID 36831689, 2023). "The ability of HDACi to regulate JAK2‐dependant signalling pathways has been largely explored in myeloproliferative neoplasms carrying the constitutively active V617F mutation." (PMID 36578217, 2023). "Hyperactive mutation V617F in the JAK2 regulatory pseudokinase domain (JH2) is prevalent in patients with myeloproliferative neoplasms." (PMID 36678572, 2023). "Especially, in this patient, a JAK2 V617F mutation with a low allele variant frequency was detected, with mutations usually associated with myeloproliferative neoplasms." (PMID 36810551, 2023). "JAK2 mutation-prevalent myeloproliferative neoplasms (MPN) include primary myelofibrosis (PMF), polycythemia vera (PV), essential thrombocythemia (ET), and MPN, unclassifiable (MPN-U)." (PMID 37460550, 2023). "Myelofibrosis (MF) is a myeloproliferative neoplasm characterized by mutations (most frequently in JAK2, CALR, or MPL), burdensome symptoms, splenomegaly, cytopenia, and shortened life expectancy." (PMID 36786879, 2023). "The discovery in 2005 of the JAK2 V617F gain-of-function mutation in myeloproliferative neoplasms and more particularly in polycythemia vera has deeply changed the diagnostic and therapeutic approaches to polycythemia." (PMID 37239426, 2023).
myeloproliferative neoplasm (continued). "Regarding the myeloproliferative disorders, it is known that JAK2, CALR, and MPL genes, which are usually associated with MPN disorders such as PMF, PV, and essential thrombocythemia (ET), have to be absent in MDS/MPN with neutrophilia." (PMID 37370785, 2023). "Lastly, a well-known pathogenic variant JAK2 p.V617F for the myeloproliferative disorder was identified in a 72-year-old woman with thrombocythemia and an undetermined subtype of stroke." (PMID 36580209, 2023). "Since 2008, the search for the JAK2 mutation (V617T) has been included as a diagnostic criterion for myeloproliferative diseases in the guidelines of the world health Organization (WHO) and is commonly sought in patients with thrombosis splanchnic." (PMID 37238951, 2023). "Initially indicated for myeloproliferative diseases secondary to somatic JAK2 gain of function mutations, JAKis were then developed for many diseases in adulthood, especially rheumatic diseases, and have been used this last decade." (PMID 37510809, 2023). "The JAK2 V617F mutation, which is associated with myeloproliferative disorders and EPO hypersensitivity, was identified exclusively in blasts of TgSpi1FA+/+ mice, including #445 and #451, with VAF values of 28 and 18%, respectively." (PMID 37573408, 2023). "From these, 81% were diagnosed with myeloproliferative disease and 76% carried driver mutations JAK2, CALR, or MPL." (PMID 36698617, 2023). "JAK2 p.V617F is a mutation commonly found in myeloproliferative neoplasms but rarely identified in non-small cell lung cancer (NSCLCs)." (PMID 35844327, 2022). "For example, the pathognomonic JAK2‐V617F mutation underlies the manifestation of myeloproliferative neoplasms." (PMID 35438189, 2022). "Recently, our group reported on a novel role of YBX1 in JAK2-mutated myeloproliferative neoplasms (MPN)." (PMID 34465866, 2022). "JAK2 V617F mutation was the first and the most well-characterized driver mutation in myeloproliferative neoplasm." (PMID 35237453, 2022). "Recently, our group identified YBX1 as a mediator of disease persistence in JAK2-mutated myeloproliferative neoplasms." (PMID 34465866, 2022). "For example, JAK2 V617F, an activating mutation, causes polycythemia vera, the most common form of myeloproliferative neoplasm (MPN)." (PMID 35851582, 2022). "Clinicopathological characteristics of myeloproliferative neoplasm cases with JAK2 and CALR Mutational status with CAL2IHC." (PMID 34514582, 2022). "Somatic mutations in JAK2 constitute a major diagnostic criterion for myeloproliferative neoplasms (MPN) and are found in approximately 95% of polycythemia vera cases and 50% of essential thrombocythemia and primary myelofibrosis." (PMID 36428627, 2022). "Most cases of myeloproliferative neoplasm are known to harbour driver mutations JAK2, MPL, or CALR in a mutually exclusive manner." (PMID 35237453, 2022). "A variant of JAK2 has also been associated with an increased risk of developing myeloproliferative neoplasms such as polycythemia vera, essential thrombocythemia and primitive myelofibrosis." (PMID 35872888, 2022). "The only myeloproliferative neoplasm included in this review presented with a JAK2 and a DNMT3A variant." (PMID 35884491, 2022). "In JAK2-mutated myeloproliferative neoplasm cells, JAK2-dependent phosphorylation of YB-1 at S30/34 maintains its nuclear proportion and splicing function." (PMID 35406781, 2022). "In 2005, the discovery of JAK2 mutation (JAK2V617F) in myeloproliferative neoplasms has attracted much attention." (PMID 35631587, 2022). "JAK2 mutations have been proved to be the cause of several hematologic disorders such as myeloproliferative neoplasm, thrombocytopenia, and polycythemia Vera." (PMID 35250656, 2022). "Double JAK2 mutations have rarely been described in myeloproliferative neoplasms (MPNs) and are demonstrated to be associated with the polycythemia vera (PV) phenotype." (PMID 36483035, 2022).
myeloproliferative neoplasm (continued). "This domain has been shown to be necessary for receptor interaction and JAK2 activation, as the oncogenic JAK2 V617F mutation within the pseudokinase domain, found in myeloproliferative neoplasms, requires an intact SH2 domain." (PMID 35089929, 2022). "It has been reported in previous studies that, in myeloproliferative neoplasms, the presence of a Janus kinase 2 (JAK2) mutation is associated with an increase in free oxygen radicals and, consequently, DNA damage is increased." (PMID 35145818, 2022). "JAK2 is frequently mutated in the aging hematopoietic system and in myeloid cancers, such as myeloproliferative neoplasms (MPN)." (PMID 35654819, 2022). "Fedratinib is a JAK2 inhibitor and has been used in treatment for patients with myeloproliferative neoplasm-associated myelofibrosis." (PMID 35773269, 2022). "VAFs of the JAK2 V617F variant, commonly found in myeloproliferative neoplasm, were 37.7 and 46.1% in ctDNA testing and germline sequencing, respectively." (PMID 35870019, 2022). "Neutrophils of patients with myeloproliferative neoplasms characterized with a constitutively activating mutation of janus kinase 2 (JAK2) are also primed to generate NETs." (PMID 35574410, 2022). "The most frequent and well-studied JAK2 mutation is JAK2-V617F, which has been reported to be associated with predisposition to myeloproliferative disorders." (PMID 35954343, 2022). "The JAK2-V617F mutation activates JAK/STAT signaling pathway which has a role in the progression of myeloproliferative disorders MPD)." (PMID 35011562, 2022). "A large number of patients with myeloproliferative disorders have been found to carry a dominant JAK2 mutation." (PMID 35453637, 2022). "Six of the significant (after Bonferroni correction) variant-level associations involve the JAK2 V617F variant, for rare diseases that can be broadly categorized as myeloproliferative disorders." (PMID 35945607, 2022). "The UKB has also been analyzed more broadly, with rare variants in JAK2 and F11 associated to groups of myeloproliferative disease and congenital coagulation defects, respectively." (PMID 35945607, 2022). "Other important hotspots include mutations linked to myeloproliferative disorders, including JAK2 (V617F) and MPL (W515L)." (PMID 36316687, 2022). "As a downstream target of these proteins, we found JAK2, a well-studied player in myeloproliferative diseases, with known mutations and hypermethylation events." (PMID 35213534, 2022). "Diagnostic and treatment response criteria for the JAK2/CALR/MPL mutation-related myeloproliferative neoplasms (MPNs) are largely based on bone marrow (BM) biopsy results." (PMID 33879266, 2021). "These myeloproliferative neoplasms are characterized by hyperactivation of janus kinase 2 (JAK2)-signaling as a result of mutations in three specific genes: JAK2, calreticulin (CALR), and myeloproliferative leukemia virus (MPL)." (PMID 34831257, 2021). "In our study, we focused on the expression of CD9 in myeloproliferative neoplasms—specifically those linked to the JAK2 (V617F) mutation, such as polycythemia vera, and essential thrombocythemia." (PMID 33918035, 2021). "In myeloproliferative neoplasms, CA upregulates SE-associated genes that mediate hematopoiesis, tumor growth inhibition, and differentiation of JAK2-mutant megakaryocytes." (PMID 34298959, 2021). "The JAK2 V617F mutation is associated with a group of hematopoietic malignancies termed myeloproliferative neoplasms (MPN), including polycythemia vera (PV), essential thrombocythemia (ET) and primary myelofibrosis (PMF)." (PMID 34368123, 2021). "Hyperactivating JAK2 mutations are the key drivers of myeloproliferative neoplasms (MPNs), a group of diseases characterized by abnormal proliferation of hematopoietic progenitor cells in the bone marrow." (PMID 33672930, 2021).
myeloproliferative neoplasm (continued). "Mutations in JAK2 are also seen in myeloproliferative neoplasms, which have also been associated with increased rates of arterial thrombotic events, including MI." (PMID 34988471, 2021). "Human myeloproliferative neoplasms (MPNs) were discovered to be associated with a unique acquired somatic mutation in JAK2 (JAK2 V617F) that constitutively activates JAK2." (PMID 34588425, 2021). "Decreased expression or TPO-MPL function results in thrombocytopenia, whereas hyperactivation of MPL signalling (due to TPO receptor mutation or JAK2 mutation) results in myeloproliferative neoplasms (MPNs)." (PMID 34681577, 2021). "In 2016, the World Health Organization (WHO) classification of myeloproliferative neoplasms specifically recognized the JAK2 V617F mutation as one of the main diagnostic criteria of Philadelphia-negative MPNs." (PMID 34436049, 2021). "JAK2–JAK2V617F—This is a point mutation of the JAK2 gene and results in myeloproliferative disorders with a polycythemia-like phenotype and increased erythropoietin-independent red blood cell production and splenomegaly." (PMID 34681039, 2021). "A pathogenic JAK2 p.V617F mutation in a patient with previously diagnosed myeloproliferative disease was excluded from further analysis." (PMID 34876602, 2021). "Nearly half of the patient population suffers from a myeloproliferative disorder in which a Janus kinase 2 (JAK2) mutation can be detected in peripheral granulocytes or hyperplastic megakaryocytes in the bone marrow." (PMID 34441027, 2021). "JAK2 is also a clinically relevant gene due to the causal link between activating JAK2 mutations and myeloproliferative disorders." (PMID 33682794, 2021). "JAK2 has been widely known for its high mutation in myeloproliferative neoplasms (~ 96% cancer patients with V617 mutation in exon 14 of JAK2)." (PMID 32513155, 2020). "PV is one of the myeloproliferative neoplasms that is characterized by an increased red cell mass and uncontrolled formation of blood cells owing to an acquired mutation in Janus kinase-2." (PMID 33312802, 2020). "Detection of the Janus Kinase-2 (JAK2) V617F mutation is a diagnostic criterion for myeloproliferative neoplasms, and high levels of mutant alleles are associated with worse outcomes." (PMID 32178286, 2020). "The prevalence of JAK2 mutation is low in the general population but higher in patients with myeloproliferative neoplasms." (PMID 32685224, 2020). "The Janus kinase 2 (JAK2)-driven myeloproliferative neoplasms (MPNs) are associated with clonal myelopoiesis, elevated risk of death due to thrombotic complications, and transformation to acute myeloid leukemia (AML)." (PMID 33329600, 2020). "Herein, we report two independent cases of severe hypertension in JAK2 mutation-positive myeloproliferative neoplasms." (PMID 33505762, 2020). "Hematopoietic neoplasms with chromosomal translocations involving JAK2 are rare, and most of them show myeloproliferative neoplasm‐associated features, followed by B‐acute lymphoblastic leukemia (B‐ALL)." (PMID 31885183, 2020). "Whilst JAK2 mutation is associated with myeloproliferative neoplasms, it has been identified in asymptomatic clonal haematopoiesis (CH), a, expansion of clonal haematopoietic cells but without diagnostic criteria for a haematologic disease present." (PMID 32823933, 2020). "JAK2 mutations were also found associated at high frequency with other myeloproliferative disorders such as essential thrombocythemia and primary myelofibrosis." (PMID 33114351, 2020). "Lastly, in 1 patient, BM findings diagnosed the previously unrecognized myeloproliferative disorder polycythemia vera harboring the JAK2 gene mutation." (PMID 33144848, 2020). "A breakthrough in understanding myeloproliferative diseases occurred after the discovery of GOF mutations in JAK2, leading to the development of small-molecule inhibitors of JAK2 for the treatment of MPNs." (PMID 31963765, 2020).